VCP (valosin containing protein)
Diseases named in the same sentence as VCP in open-access papers (continued):
Sharing a sentence is not in itself a finding about the gene and the disease.
amyotrophic lateral sclerosis (continued). "Recently, the list of degenerative disorders that are associated with VCP mutations has expanded to include amyotrophic lateral sclerosis (ALS), spastic paraplegia, scapuloperoneal muscular dystrophy and Charcot-Marie-Tooth disease." (PMID 26167652, 2015). "Mutations in the VCP gene were later reported to occur in familial amyotrophic lateral sclerosis (ALS)." (PMID 25492614, 2014). "VCP gene mutations have also been linked to 2% of isolated familial amyotrophic lateral sclerosis (ALS)." (PMID 23029473, 2012). "Genome-wide association studies have linked PI31 to AD risk, and a direct antagonist of PI31, called valosin-containing protein (VCP), causes a familial type of the neurodegenerative disorder amyotrophic lateral sclerosis." (PMID 39990094, 2024). "Reports also underscore the roles of proteins found in ADEVs, such as valosin-containing protein and peptidyl-prolyl cis-trans isomerase A (Cyclophilin A) in amyotrophic lateral sclerosis (ALS) and frontotemporal lobar degeneration." (PMID 37728588, 2024). "Finally, mTOR (mechanistic target of rapamycin) dysfunction has been identified as a contributing factor in human diseases such as amyotrophic lateral sclerosis (ALS), which was found to be associated with VCP mutations." (PMID 35743185, 2022). "Mutations in Valosin Containing Protein (VCP) are associated with several degenerative diseases, including multisystem proteinopathy (MSP-1) and amyotrophic lateral sclerosis." (PMID 34160014, 2021). "VCP/p97 mutations also account for 1%–2% of the familial amyotrophic lateral sclerosis (ALS) cases." (PMID 33439255, 2021). "Skin immunohistochemical studies on patients with amyotrophic lateral sclerosis (ALS) have shown that increased VCP expression correlates with the progression of this neurodegenerative disease." (PMID 32602849, 2020). "Mutations in VCP contribute to FTD, amyotrophic lateral sclerosis, inclusion body myositis and Paget’s disease; mutations in PINK1 elicit motor and cognitive dysfunction characteristic of early-onset PD/PDD." (PMID 30783609, 2018). "The genes for four proteins involved in this process (TDP43, FUS, VCP, and CHMP2B) have mutations in various familial cases of the neurodegenerative diseases fronto-temporal dementia (FTD) or amyotrophic lateral sclerosis (ALS)." (PMID 27242399, 2016). "Familial forms of FTLD-tau are associated with mutations in the MAPT gene that encodes the tau protein, whilst mutations in Granulin (GRN), Valosin Containing Protein (VCP), or C9ORF72 genes can cause FTLD-TDP or amyotrophic lateral sclerosis." (PMID 23666556, 2013). "Mutations in the valosin-containing protein (VCP) gene cause various lethal proteinopathies that mainly include inclusion body myopathy with Paget’s disease of bone and frontotemporal dementia (IBMPFD) and amyotrophic lateral sclerosis (ALS)." (PMID 35501124, 2022). "Mutations in VCP lead to (cardio-)myopathy and neurodegenerative diseases such as inclusion body myopathy with Paget’s disease of the bone and frontotemporal dementia (IBMPFD) or amyotrophic lateral sclerosis (ALS)." (PMID 35743185, 2022). "Moreover, VCP-positive inclusion bodies have been found in several neurodegenerative diseases, such as Parkinson’s disease, amyotrophic lateral sclerosis (ALS) and spinocerebellar ataxia type 3." (PMID 34359848, 2021). "However, VCP mutations have also been documented in patients with amyotrophic lateral sclerosis (ALS), Charcot-Marie-Tooth type 2 (CMT2) disease, and hereditary spastic paraplegia (HSP), underlining the heterogeneity of the phenotypes due to VCP mutations." (PMID 34917136, 2021). "In addition to these three degenerative conditions, amyotrophic lateral sclerosis (ALS) and Parkinson's disease are linked to VCP mutations." (PMID 34160014, 2021).
amyotrophic lateral sclerosis (continued). "VCP gene is associated with the multisystem degenerative autosomal dominant disorder of inclusion body myopathy with Paget disease of bone and frontotemporal dementia (IBMPFD) and mutations were related to 1–2% of amyotrophic lateral sclerosis cases." (PMID 32858845, 2020). "Mutations in VCP cause multisystem proteinopathy (MSP), with among its spectrum of symptoms frontotemporal dementia, as well as the motor neuron disease amyotrophic lateral sclerosis (ALS)." (PMID 25132814, 2014). "Specific links between VCP-complexes have been established or predicted for neurodegeneration in general, amyotrophic lateral sclerosis (ALS), Parkinson’s disease (PD), Alzheimer’s disease (AD), Huntington’s disease (HD) and others." (PMID 37545006, 2023). "Amyotrophic lateral sclerosis (ALS) is characterised by the presence of genetic mutations in autophagy-related genes, including SQSTM1, OPTN, TBK1, VCP, and C9ORF72, which have been found to be linked to family variants of the illness." (PMID 37760929, 2023). "Additionally, some cases of PDB-like syndromes have been attributed to mutations in VCP, TNFRSF11A, TNFRSF11B, HNRNPA2B1, HNRNPA1, ZNF687 and PFN1, most of which are known to involved in the amyotrophic lateral sclerosis (ALS) and nuclear factor kappa B (NF-kB) signaling pathways." (PMID 35355568, 2022). "Mutations in VCP predispose humans to amyotrophic lateral sclerosis (ALS) and frontotemporal degeneration dementia (FTD), and VCP-associated ALS/FTD is characterized by ubiquitin-positive cytoplasmic inclusions containing TDP-43." (PMID 36498892, 2022). "Missense mutations in Valosin-Containing Protein (VCP) are linked to diverse degenerative diseases including IBMPFD, amyotrophic lateral sclerosis (ALS), muscular dystrophy and Parkinson’s disease." (PMID 33479240, 2021). "Among these genes, mutations in VCP gene involve in inclusion body myopathy with Paget disease of bone and frontotemporal dementia (IBMPFD), familial amyotrophic lateral sclerosis (ALS), autism spectrum disorders (ASD), and hereditary spastic paraplegia (HSP)." (PMID 29310658, 2018). "Mutations in the VCP gene result in inclusion body myopathy with Paget's disease of bone and frontotemporal dementia (IBMPFD) and amyotrophic lateral sclerosis (ALS)." (PMID 22449146, 2012). "Moreover, other neurological manifestations like amyotrophic lateral sclerosis (ALS), progressive spastic paraplegia, distal myopathy, facio–scapulo–humeral weakness, parkinsonism, Charcot–Marie–Tooth disease and Huntington’s disease have been described in association with pathogenic VCP–variants." (PMID 36289705, 2022). "Similar effect can be observed in the case of Amyotrophic Lateral Sclerosis: SOD1 has the highest betweenness centrality, followed by VCP and DCTN1 with almost twice as much lower betweenness." (PMID 25528190, 2014). "Mutations in the valosin containing protein (VCP) gene lead to Inclusion body myopathy associated with Paget's disease of bone and frontotemporal dementia (IBMPFD) and more recently affect 2% of amyotrophic lateral sclerosis (ALS)-diagnosed cases." (PMID 24130765, 2013). "Numerous mutations in the VCP gene have been linked with genetic disorders such as Inclusion Body Myopathy with Paget's disease of bone and Fronto-temporal Dementia (IBMPFD) and familial Amyotrophic Lateral Sclerosis (ALS)." (PMID 23349634, 2013). "Mutations in the VCP gene have been linked to autosomal dominant disorders Inclusion Body Myopathy with Paget's disease of bone and Fronto-temporal Dementia (IBMPFD) and familial Amyotrophic Lateral Sclerosis (ALS)." (PMID 23349634, 2013). "In particular, variants in VCP cause a specific type of FTLD, inclusion body myopathy associated with Paget disease of bone and frontotemporal dementia (IBMPFD) and amyotrophic lateral sclerosis (ALS), also referred to as multisystem proteinopathy type 1 (MSP1)." (PMID 39629589, 2024).
amyotrophic lateral sclerosis (continued). "Mutations in VCP are known to cause neuromuscular diseases such as inclusion body myopathy with Paget’s disease of bone and frontotemporal dementia (IBMPFD) and amyotrophic lateral sclerosis (ALS), and also striated muscle diseases such as myofibrillar myopathies (MFMs)." (PMID 35743185, 2022). "Mutations in VCP have been connected to neurodegenerative multisystemic proteinopathies in humans, such as inclusion body myopathy with Paget disease of bone and frontotemporal dementia (IBMPBFD), amyotrophic lateral sclerosis (ALS), and Charcot-Marie-Tooth disease type 2 (CMT2)." (PMID 33297935, 2020). "Moreover, VCP has been shown to be involved in pathogenesis of wide variety of neurodegenerative diseases including Alzheimer's disease, Parkinson's disease and Amyotrophic Lateral Sclerosis (ALS), possibly via regulation of ER homeostasis." (PMID 25970786, 2015). "Amyotrophic lateral sclerosis (ALS) and frontotemporal dementia share genetic disruptions (for example, C9orf72, OPTN, VCP, TMEM106B and progranulin (PGRN)) that impair normal Golgi–endolysosomal trafficking, severely reducing intracellular protein handling and degradation capabilities." (PMID 41254240, 2025).
Paget’s disease of bone (57 papers, 2008 to 2025). "Studies on patients with VCP mutations report that myopathy, Paget’s disease of bone, and FTD were present in 90%, 42%, and 30% of the patients, respectively, while approximately 9% of patients exhibited an ALS phenotype and 4% were diagnosed with PD." (PMID 40282367, 2025). "Variants in the valosin-containing protein (VCP) gene were identified as one of the causes for inclusion body myopathy (IBM) associated with Paget disease of the bone (PDB) and FTD (IBMPFD)." (PMID 36329418, 2022). "Type D is always associated with a multisystem proteinopathy caused by mutations in the valosin-containing protein (VCP) gene, which cause a variable phenotypical expression of inclusion-body myopathy, Paget’s disease of the bone, and FTD." (PMID 34389969, 2021). "FTD in combination with inclusion body myopathy and Paget’s disease of bone in the patients or families strongly suggests mutations in the VCP, hnRNPA1, or MATR3 genes." (PMID 26213621, 2015). "Mutations in human p97 (known as VCP) are linked to neurodegenerative disorders, such as amyotrophic lateral sclerosis and inclusion body myopathy associated with Paget disease of bone and frontotemporal dementia (IBMPFD)." (PMID 24598262, 2014). "Six missense mutations in VCP (Valosin-containing protein) gene is identified in IBMPDF (inclusion body myopathy associated with Paget disease of bone and FTD)." (PMID 21416021, 2009). "Other uncommon mutations have been identified in the valosin-containing protein (VCP) gene, which cause inclusion body myopathy with Paget disease of bone and FTD, and in the charged multivesicular body protein 2B (CHMP2B) gene, involved in the endosomal–lysosomal pathway." (PMID 26388768, 2015). "Interestingly, the complexity of the biological interaction between muscle and bone is further supported by the evidence that about 50% of patients with inclusion body myositis caused by valosin-containing protein (VCP) gene mutation develop Paget's disease of bone." (PMID 31824418, 2019). "Valosin-containing protein (VCP) gene mutations, located on chromosome 9, have been linked to a multisystem disorder characterized by early Paget disease of the bone, inclusion body myopathy (IBM), and FTD." (PMID 40722695, 2025). "Paget's disease of bone (PDB) is a common skeletal disorder characterized by abnormal focal bone remodeling, in which VCP is a susceptibility gene in PDB pathogenesis." (PMID 37606987, 2023). "Pathogenic VCP gene variants are associated with the characteristic clinical picture of IBM, FTD and ALS, often with Paget’s disease of bone." (PMID 34573259, 2021). "VCP is known to associate with some forms of FTD, Paget's disease of the bone (PDB) and inclusion body myopathy (IBM) before the discovery that mutations in these same genes account for approximately 1–2% fALS patients." (PMID 28282387, 2017). "Mutations in the valosin-containing protein (VCP) gene constitute another rare cause of FTD, which has been recognized to present with the clinical syndrome of “IBMPFD” (inclusion body myopathy, Paget’s disease of bone and FTD), often in combination with ALS in certain families." (PMID 36294886, 2022).
Parkinson disease (35 papers, 2010 to 2026). A progressive degenerative disorder of the central nervous system characterized by loss of dopamine producing neurons in the substantia nigra and the presence of Lewy bodies in the substantia nigra and locus coeruleus. "Despite the negative findings in that study, several case reports link specific pathogenic VCP variants to parkinsonism." (PMID 41277110, 2026). "Parkinson disease and Alzheimer disease have been associated with VCP mutations, although it is important to be aware that these conditions are also common in the aged population." (PMID 35741724, 2022). "Neurodegenerative diseases associated with a VCP mutation encompass scapuloperoneal muscular dystrophy and dropped head syndrome, Parkinson’s disease, hereditary spastic paraplegia, and cerebellar ataxia." (PMID 25492614, 2014). "While VCP mutations resulting in parkinsonism are rare—in one study of 231 patients with 15 different VCP mutations, 3.8 % of patients had parkinsonism —it is an important emerging link that should be considered in patients with both neuromuscular disorders and parkinsonism phenotypes." (PMID 38145206, 2024). "There are also descriptions of VCP variants associated with Parkinson’s disease." (PMID 38891822, 2024). "Parkinsonism is presented in familial ALS cases with VCP p.R191G mutation." (PMID 35197922, 2022). "Additionally, a link is supported by the finding of a greater prevalence of PD/parkinsonism in those with VCP mutations." (PMID 35093159, 2022). "Other neurodegenerative conditions may be more common in patients with VCP mutations, including Parkinson disease and Alzheimer disease." (PMID 35741724, 2022). "Also VCP is known as detector of aggregated proteins causing neurodegenerative disease such as Parkinson and Alzheimer." (PMID 23233838, 2012). "VCP/p97 is associated with the various cellular pathologies and disease states including neurodegenerative disorders (Creutzfeldt-Jacob, Alzheimer's, and Parkinson's diseases), pulmonary conditions and other protein misfolding disorders." (PMID 22216170, 2011). "Notably, the R191Q VCP mutation has been specifically related to parkinsonism, which might be the only initial symptom." (PMID 40722695, 2025). "Furthermore, parkinsonism has been reported in several VCP mutation carriers." (PMID 38145206, 2024). "In addition, mutations in the endo-lysosomal trafficking machinery have been implicated in neurodegenerative disorders including ALS and FTD (CHMP2B, FIG4, VAPB, and VCP) and defects in retrograde trafficking increase the risk for Parkinson's disease (VPS35)." (PMID 26357016, 2015). "Further linking VCP to another neurodegenerative disease, it is also notable that PINK1 and Parkin are encoded by Parkinson’s disease genes." (PMID 38891822, 2024). "It has been reported that p97/VCP plays a role in pathologies such as neurodegenerative disorders (Creutzfeldt-Jakob, Alzheimer’s, Parkinson’s disease), pulmonary pathologies, protein misfolding disorders, Paget’s disease and retinal degeneration." (PMID 37374283, 2023). "The relevance of VCP mutations for the onset and the progression of multisystemic degenerative diseases such as IBMPFD, ALS, Parkinson’s disease, or MFMs has been demonstrated by many in vitro and in vivo studies." (PMID 35743185, 2022). "Co-occurrence of FTD, PDB, parkinsonism, myopathy, or psychiatric diseases was reported in 18 (39.1%, 18/46) ALS cases carrying VCP mutations." (PMID 35197922, 2022). "The co-occurrence of FTD, PDB, parkinsonism, myopathy, or psychiatric diseases was commonly seen in the ALS cases carrying VCP mutations." (PMID 35197922, 2022). "Approximately 9% of patients with VCP mutations had ALS phenotype, 4% with Parkinson's disease, and 2% has been diagnosed with Alzheimer's." (PMID 34918006, 2022).
Parkinson disease (continued). "Akinetic–rigid parkinsonism, as far as TDP-43 proteinopathies are concerned, occurs commonly in PGRN mutations and is rather uncommon in C9orf72 mutations and VCP (Valosin Containing Protein) mutations and rare in TARDP mutations cases." (PMID 34943897, 2021). "VCP mutations are also linked to other degenerative diseases, including ALS, Parkinson's disease and muscular dystrophy." (PMID 34160014, 2021). "Mutations in VCP are known to cause IBMPFD, Parkinson's disease, and are also associated with ALS with or without FTD." (PMID 27594680, 2016). "The inclusion of VCP in panels for common neurodegenerative disorders such as Alzheimer and Parkinson disease may also be reasonable, but clinical judgement is required in test result interpretation for these disorders which are common in the aged population." (PMID 35741724, 2022). "In Parkinson’s disease miR-5701 was reported to modulate mitochondrial-lysosomal cross talk, targeting genes involved in lysosomal biogenesis and mitochondrial quality control (VCP, LAPTMA4A, ATP6V0D1)." (PMID 34827683, 2021). "VCP immunoreactivity has been observed in Lewy bodies in Parkinson’s disease and dementia with Lewy bodies, in neuronal nuclear inclusions in polyglutamine diseases and intranuclear inclusion body disease, in Marinesco bodies, and in epidermal cells from patients with SALS." (PMID 25492614, 2014). "Four other less common genetic links reported in familial FTD with parkinsonism cases are—chromatin modifying protein 2B (CHMP2B), transactive response DNA-binding protein (TARDBP), valosin-containing protein (VCP), and fused-in-sarcoma (FUS) genes." (PMID 33250855, 2020). "In a wide variety of diseases such as Parkinson’s disease, Hungtinton’s disease, Lewy Body disease, ALS and Machado-Joseph disease, VCP/p97 positive aggregates were observed." (PMID 27768726, 2016). "Since then, mutations in several other genes have been identified for FTLD with parkinsonism, including chromatin modifying protein 2B, chromosome 9 open reading frame 72 (C9ORF72), fused in sarcoma, valosin-containing protein, and transactive DNA-binding protein (TARDBP)." (PMID 29881367, 2018). "VCP co-localizes with aggregated Ataxin-3, TDP-43 or with ubiquitinated inclusions in Alzheimer's and Parkinson's disease suggesting that modulation of VCP activity might have a broad relevance for protein clearance (including neurodegenerative) disorders." (PMID 20865169, 2010).